PRMT1 (protein arginine methyltransferase 1)
Diseases named in the same sentence as PRMT1 in open-access papers (continued):
Sharing a sentence is not in itself a finding about the gene and the disease.
cancer (continued). "Elevated PRMT1 expression is found in several cancer types and is associated with poor prognosis and chemoinsensitivity and pharmacological PRMT inhibitors have recently gained interest as drug candidates for cancer treatment." (PMID 33575256, 2020). "Protein arginine methyltransferase 1 (PRMT1) catalyzing the formation of asymmetric dimethylarginines has been implicated in cancer development, metastasis, and prognosis." (PMID 30741995, 2019). "PRMT1 is the most abundant arginine methyltransferase in human cells and has been linked to some cancers, including MLL, with varying expressions of every isoform." (PMID 22839530, 2012). "The dysregulation of PRMT1 is associated with the occurrence and development of various diseases, including pulmonary fibrosis, cardiovascular disease, diabetes, nephropathy, and cancer." (PMID 39906150, 2025). "Consequently, PRMT1 dysregulation is implicated in the pathogenesis of numerous human diseases, including cancer, cardiovascular disorders, and neurodegenerative and immunological conditions." (PMID 41256732, 2025). "Thus, PRMT1 is implicated in the pathogenesis of cancer and neurological diseases through its role in regulating RNA splicing." (PMID 41256732, 2025). "Furthermore, the excessive expression of PRMT1 is linked to the conspicuous proliferation, invasion, and metastasis of tumorous cells, hence making it a crucial protein in cancer development." (PMID 38326807, 2024). "In cancer, PRMT1 was found to be associated with lower efficacy of chemotherapy." (PMID 39703687, 2024). "Due to the substrate of PRMT1 regulate various biological functions, the dysregulation of arginine methylation caused by PRMT1 may lead to the progression of cancer." (PMID 39749343, 2024). "Elevated levels of PRMT1 are linked to poor prognosis in many cancer types." (PMID 39620228, 2024). "PRMT1 upregulation has been linked to numerous cancer types 67-70." (PMID 37564212, 2023). "PRMT1 dysfunction is closely associated with various kinds of cancers." (PMID 36151091, 2022). "Here, we argue that targeting PRMT1, which blocks the generation of immune Mks and their pathogenic platelet progenies, may create a hostile tumor microenvironment for cancer cells to adapt to." (PMID 36152748, 2022). "All these proteins are implicated in cancer progression through DNA damage response and signaling pathways, and their interaction with PRMT1 transcripts could be critical to their complex functions." (PMID 35885916, 2022). "However, it does not appear to be the case that PRMT1 mutations are generally rare in cancers, with 9.0% (1024/11,315) of samples in The Cancer Genome Atlas (TCGA) harboring PRMT1 mutations." (PMID 34688662, 2021). "As a way of linking the fundamental requirement for dimerization with biological consequences, we sought to identify if there were any mutations to the PRMT1 dimerization arm that might disrupt activity in characterized cancer cells." (PMID 34688662, 2021). "Additionally, there are other examples of cancers in which decreased PRMT1 expression or PRMT1 knockdown is associated with worse outcomes." (PMID 34688662, 2021). "As such, MTAP-deficient cancer cells are inherently sensitive to inhibition of PRMT1." (PMID 33691794, 2021). "Given the link between PRMT1 dysregulation and disease and the link between PRMT1 dimerization and activity, we searched the Catalogue of Somatic Mutations in Cancer (COSMIC) database to identify potential inactivating mutations occurring in the PRMT1 dimerization arm." (PMID 34688662, 2021). "Furthermore, the disordered expression of PRMT1 is associated with a variety of human diseases including pulmonary fibrosis, cardiovascular diseases, diabetes, renal diseases and cancer in particular." (PMID 31390828, 2019). "As an aberrant regulation of the Wnt pathway is a driver of many different cancers, it is tempting to speculate that a dysregulation in the expression of PRMT1 could be linked with tumorigenesis." (PMID 27556302, 2016).
cancer (continued). "Increasing evidence has linked PRMT1 to the development and progression of cancers." (PMID 26813495, 2016). "While DDR helps preserve genomic integrity in normal cells, it may provide resistance to DNA damage caused by radiotherapy and chemotherapy in cancer cells, leading to drug resistance and highlighting the possible involvement of PRMT1 in therapeutic resistance in tumors." (PMID 41256732, 2025). "PRMT1 has been implicated in enhancing immune evasion, suggesting that investigations into cGAS methylation may provide novel insights into the mechanisms of cancer immunology." (PMID 40470467, 2025). "In addition, the transwell assay revealed that PRMT1 could reverse the suppression of cancer cell metastasis caused by circTBC1D14 silencing." (PMID 36806670, 2023). "Various studies have demonstrated that the overexpression of PRMT1 is common in cancer development and correlates with poor survival prognosis of patients." (PMID 42048414, 2026). "An RNA-sequencing (RNA-seq) analysis indicated that although all the PRMT family members were detectable in cancers, five PRMTs (PRMT1/2/4/5/7) exhibited remarkably high expression levels (average FPKM >10)." (PMID 38826355, 2025). "Arginine methylation appears to be a powerful target when treating cancer, yet more research needs to be carried out on the specific regulatory mechanisms behind PRMT1 to develop a widely successful inhibitor." (PMID 40869229, 2025). "The type I PRMT family includes PRMT1, PRMT2, PRMT3, PRMT4, PRMT6, and PRMT8, which have been linked to various aspects of cancer development, including carcinogenesis, metastasis, and drug resistance." (PMID 39699269, 2025). "Consistent with this notion, PRMT1 inhibitors exhibit synergistic effects with immune checkpoint blockade in enhancing cancer immunity and are currently under evaluation in phase I clinical trials." (PMID 40470467, 2025). "The dysregulation of the cell cycle and the suppression of apoptosis are fundamental characteristics of cancer, and PRMT1 is a significant contributor to both processes." (PMID 41256732, 2025). "With the current review, we aim to present an in-depth overview of how PRMT1 influences epigenetic modulation, transcriptional regulation, DNA damage repair, and signal transduction in cancer." (PMID 40001488, 2025). "Collectively, these findings demonstrate that PRMT1 facilitates cancer cell migration through R64 methylation of vimentin." (PMID 40884268, 2025). "Another study that highlighted the effect of PRMT1 on fatty acid metabolism in the context of cancer was performed recently by Yan and colleagues in HCC." (PMID 40001488, 2025). "Yet, the combination of PRMT1 knockdown with targeted drugs significantly reduced the regrowth of persistent cancer cells." (PMID 39699269, 2025). "This study reveals that PRMT1 forms functional helical oligomers that enhance substrate binding and activity, with implications for cancer cell proliferation and RNA metabolism." (PMID 40675804, 2025). "While our functional assays establish R64 as a critical determinant of vimentin filament dynamics and cancer cell migration, systematic proteomic mapping of other hypoxia‐PRMT1‐regulated methylation sites on vimentin represents an important future direction." (PMID 40884268, 2025). "GSK3368715 (also known as EPZ019997) is a selective PRMT1 inhibitor that demonstrated enhanced antitumor activity in MTAP-deleted cancer cells." (PMID 41204384, 2025). "As a type I PRMT, PRMT1 has been shown to have an important role in a variety of cancers, such as bladder, ovarian, prostate, oesophageal squamous cell carcinoma, and acute myeloid leukaemia." (PMID 39964832, 2025). "PRMT1-mediated metabolic reprogramming indicates that mitochondria in PRMT1-overexpressing cancer cells primarily function to produce biosynthetic precursors instead of generating oxidative ATP." (PMID 40801789, 2025).
cancer (continued). "While elevated PRMT1 typically correlates with a poor prognosis in many cancers, the opposite is true in non‐MYCN‐amplified neuroblastoma, where its loss predicts worse outcomes." (PMID 41256732, 2025). "This PRMT1‐vimentin R64 asymmetric demethylation (aDMA) axis drives cytoskeletal reorganization and cancer cell migratory capacity, with functional validation in xenograft models demonstrating its critical requirement for metastatic colonization." (PMID 40884268, 2025). "Recent developments targeting PRMT1 have also shown promise in advantageously regulating the type I protein arginine methyltransferase in specific cancer treatments." (PMID 40869229, 2025). "Since dysfunctions in metabolism are having a great impact on global health, science and society would benefit immensely if researchers interested in PRMT1 widened their horizons and shifted their views from cancer to the metabolic field." (PMID 40001488, 2025). "As such, the function of PRMT1 has been most prominently investigated in the context of cancer development." (PMID 40001488, 2025). "An abundance of research has reported that many different signaling pathways in cancer cells are dysregulated due to PRMT1-mediated methylation." (PMID 40001488, 2025). "The identification of PRMT1‐v6 in BC cells suggests its involvement in the deregulation of cellular processes that drive cancer progression and indicates its potential as a therapeutic target in BC." (PMID 41256732, 2025). "Beyond its roles in tumor initiation and progression, PRMT1 is increasingly recognized as a central driver of therapeutic resistance across multiple cancer types, though this understanding has yet to be fully translated into clinical applications." (PMID 41256732, 2025). "A range of cancers display aberrant protein‐arginine methylation via type I PRMTs (primarily PRMT1 and PRMT4) and type II PRMTs (principally PRMT5)." (PMID 39964832, 2025). "This review aims to provide an overview of our current knowledge regarding the established role of PRMT1 in cancer and to spark interest in the upcoming findings related to PRMT1 from the metabolic field." (PMID 40001488, 2025). "In summary, PRMT1 functions as a master epigenetic regulator of multiple DNA repair pathways, enabling tumor cells to survive genotoxic stress from cancer therapies." (PMID 41256732, 2025). "Overall, PRMT1 is a key enzyme crucial for biological functions, cancer progression, immune regulation, and chemoresistance." (PMID 40927753, 2025). "MS023, an additional PRMT1 inhibitor undergoing clinical trials, demonstrates efficacy in surpassing the requisite threshold to trigger apoptosis in cancer cells." (PMID 40869229, 2025). "Colony formation assays demonstrated that an acute knock out of PRMT1 or PRMT5 significantly increased the sensitivity levels of cancer cells to PARPi treatment, thereby phenocopying the results obtained using chemical PRMT inhibitors." (PMID 38826355, 2025). "Our findings contribute to understanding PRMT1 substrate specificity and provide a scaffold for developing potent inhibitors targeting PRMT1 in diseases, including cancer." (PMID 41301411, 2025). "In this study, we delved into the mechanisms underlying drug resistance in SCLC, identifying the pivotal role of the PRMT1/SOX2 axis in governing cancer stemness, a factor that substantially contributes to SCLC chemoresistance." (PMID 41377018, 2025). "We identified their distinct functions in cancer persistence and found that PRMT1 is the essential isoform in the type I PRMT family to target for reducing STAT1-promoted persistence." (PMID 39699269, 2025). "Nevertheless, in various malignant tumors, the aberrant overexpression or heightened activity of PRMT1 is a frequently observed feature." (PMID 41256732, 2025).
cancer (continued). "To further validate our findings and assess the clinical relevance of PRMT-1, -4, -6, and -8 in chemotherapy resistance, we analyzed patient data from the Cancer Treatment Response Gene Signature Database (CTR-DB), a publicly available resource." (PMID 40781072, 2025). "This study provides a rationale for developing PRMT1-selective inhibitors to target cancer persisters and achieve more durable outcomes in oncogene-targeting therapies." (PMID 39699269, 2025). "Together, our study pinpoints the PRMT1 isoform as a critical vulnerability of cancer persistence in EGFR- or KRASG12C-targeted therapies." (PMID 39699269, 2025). "Both cancer and metabolism research suggest that inhibiting PRMT1 would probably be the most beneficial therapy option." (PMID 40001488, 2025). "The growing body of research on PRMT1 has enhanced our understanding of its diverse substrates and its role in tumour biology, thus positioning PRMT1 as an intriguing target for new cancer therapy strategies." (PMID 39964832, 2025). "By forming a stable interaction with PRMT1, TC-E 5003 demonstrates its ability to disrupt PRMT1’s function, thereby impairing the biological processes necessary for cancer cell survival and metastasis." (PMID 40927753, 2025). "Further investigation into the precise mechanisms by which PRMT1 drives cancer progression, as well as its interaction with other therapeutic agents, will be crucial for optimizing treatment strategies." (PMID 40927753, 2025). "Together, our results identify PRMT1, within the family of type I PRMTs, as the critical isoform to target for reducing cancer persistence in EGFR- or KRASG12C-targeted therapies." (PMID 39699269, 2025). "These methylation changes can potentially be instigated by PRMT1 as high expression of PRMT1 has been documented to induce a proliferation and transformation of cancer cells in several types of cancer." (PMID 40001488, 2025). "PRMT1 has been found to regulate DNA damage repair pathways and dysregulate these in cancer environments." (PMID 40001488, 2025). "One more interesting pathway in cancer that can be disrupted by PRMT1 methylation is the pathway of the mechanistic target of rapamycin complex 1 (mTORC1)." (PMID 40001488, 2025). "Altogether, this makes PRMT1 inhibition an appealing treatment option to attenuate cancer cell proliferation and survival by disrupting DNA damage repair proteins." (PMID 40001488, 2025). "Most importantly, a meta-analysis across 33 cancer types from the TCGA cohort demonstrated that higher expressional levels of PRMT1/3/4/5 were positively correlated with shorter patient survival times." (PMID 38826355, 2025). "Collectively, these findings establish K134/K145 lactylation as indispensable for PRMT1‐mediated cancer cell migration, thereby linking this modification to metastatic progression." (PMID 40884268, 2025). "PRMT1, the isozyme responsible for the majority of asymmetric dimethylation (ADMA) is implicated in various diseases, including cancer." (PMID 41301411, 2025). "Due to its established role in cancer, this finding prompted further investigation into PRMT1 as a potential therapeutic vulnerability and survival dependency target in MM cells." (PMID 41188812, 2025). "This discovery provides new avenues for developing PRMT1‐targeted antitumor drugs and for treating cancers driven by dysregulated RNA splicing." (PMID 41256732, 2025). "In many cancers types, PRMT1 is overexpressed, and its overexpression is often correlated with cancer grade and poor prognosis." (PMID 39201539, 2024). "Some of these genes are involved in metabolic pathways including fatty acid beta-oxidation and calcification (CPT1A and PHOSPHO1) and in some cancers (PRMT1)." (PMID 37793095, 2024). "Here, we provide a comprehensive overview of the methylation substrates and functions of PRMT1 in various types of human tumors to explore its potential value in cancer therapy." (PMID 40018367, 2024).
cancer (continued). "The extensive involvement of PRMT1 in the development and progression of cancer has spurred extensive research to unravel its functions and regulatory mechanisms." (PMID 38326807, 2024). "A growing body of evidence from recent literature highlights the significance of PRMT1 in cancer research." (PMID 38326807, 2024). "As a result, there has been a surge of interest in the development of PRMT1 inhibitors as researchers strive to explore the potential of these inhibitors as cancer therapeutics." (PMID 38326807, 2024). "In the following sections, we will discuss PRMT1’s biological role in physiological processes, cancer, and innate immunity." (PMID 40018367, 2024). "The functions and regulatory mechanisms of PRMT1 in cancer progression have been extensively studied to uncover potential PRMT1-dependent therapeutic strategies, and please refer to the review articles for details." (PMID 40018367, 2024). "PRMT1 is the most prevalent arginine methyltransferase, and its expression is dysregulated in cancer." (PMID 38326807, 2024). "The overexpression of PRMT1 in fresh HCC tissues has been associated with EMT, considered one of the hallmarks of cancer." (PMID 38326807, 2024). "The study of PRMT1 inhibitors has thus become a prominent area of focus in the quest for effective treatments against cancer." (PMID 38326807, 2024). "Collectively, these findings underscore the multifaceted role of PRMT1 in cancer development and progression, impacting metabolism, cell division, EMT, and chemotherapeutic response." (PMID 38326807, 2024). "PRMT1 is also known to regulate the EMT-signaling pathway in cancer cells, suggestive of its involvement in tumor metastasis." (PMID 38612768, 2024). "The intricate involvement of PRMT1 in these processes underscores its significance in understanding the fundamental mechanisms of cancer onset and advancement, as well as its potential in predicting prognosis." (PMID 38326807, 2024). "PRMT1 contributes to the immune escape of cancer, and PRMT1 inhibition can activate the antitumor immunity." (PMID 38918785, 2024). "Many studies have shown that PRMT1 also acts as a tumor suppressor to prevent the occurrence of cancer." (PMID 38326807, 2024). "These two compounds display significant inhibitory effects on PRMT1 and inhibitory properties on the growth of tested cancer cell lines, with ZJG51 having relatively stronger activities against cancer cells." (PMID 39201539, 2024). "The role of PRMT1 in promoting invasion or metastasis of other type of cancers is also well recognized." (PMID 38612768, 2024). "In PDAC, treatment with PRMT1 inhibitors is cytotoxic, consistent with an increased dependency of cancer cells on protein synthesis." (PMID 37673892, 2023). "The inhibition of PRMT5 as well as PRMT1 and CARM1 have been shown to cause splicing inhibition and display anti-cancer properties in several cancers." (PMID 37568815, 2023). "These analysis results showed higher expression of PRMT1 in almost all cancer types, including GC, than in the corresponding normal tissues." (PMID 37564212, 2023). "Although several studies are dedicated to elucidating the role of EMT in cancer progression and tumorigenicity, the role of p120-catenin and PRMT-1 in TKI resistance is minimally studied." (PMID 37444572, 2023). "Despite of regulating cancer cell proliferation and apoptosis, we provide another mechanism driven by PRMT1, in which PRMT1 inhibits necroptotic cell death." (PMID 37005412, 2023). "The inhibition of PRMT1 suppressed the cancer cells' growth when exposed to low doses of cisplatin, which sensitized them to apoptosis." (PMID 37737256, 2023). "PRMT1 overexpression promotes the survival and invasion of cancer cells, whereas PRMT1 suppression inhibits the proliferation of cancer cells." (PMID 37569634, 2023). "Since PRMT1 has been more extensively studied in cancer than PRMT3, we focused on exploring the function of PRMT3." (PMID 37973560, 2023).